RN7SL469P (RNA, 7SL, cytoplasmic 469, pseudogene)
Gene: Miscellaneous RNA gene on chromosome 15 (30,143,733 to 30,143,969, forward strand). Ensembl gene ENSG00000277637.
Homologues: Orthologues: pig Metazoa_SRP (59% identical). Paralogues in human: RN7SL673P (100% identical), RN7SL628P (99% identical), RN7SL719P (99% identical), RN7SL82P (99% identical), RN7SL495P (99% identical), RN7SL185P (98% identical), RN7SL196P (97% identical), RN7SL286P (97% identical), RN7SL539P (97% identical), RN7SL796P (97% identical), Metazoa_SRP (92% identical), RN7SL106P (92% identical), and 709 more.